TMPRSS2 (transmembrane serine protease 2)
Diseases named in the same sentence as TMPRSS2 in open-access papers (continued):
Sharing a sentence is not in itself a finding about the gene and the disease.
diabetes (30 papers, 2020 to 2025). "The HT-SARS-CoV-2 ACE2 and TMPRSS2 were positively associated with healthy pancreatic tissue, while a non-significant positive association was noted in the context of cancer and diabetes mellitus." (PMID 33796097, 2021). "Furthermore, during SARS-CoV-2 infection, TMPRSS2 expression significantly decreases, while pre-existing conditions, like diabetes, obesity, Barrett’s esophagus or autoimmune disease, show higher TMPRSS2 expression and are associated with a more severe course of SARS-CoV-2." (PMID 36830955, 2023). "While cathepsin L is downregulated in diabetes, and furin has been shown to be both up- and downregulated in serum, expression of the TMPRSS2 in cardiomyocytes increases in diabetes." (PMID 39273582, 2024). "The following variables were included: TMPRSS2 rs2070788 genotypes, sex, age, diabetes, hypertension, chronic heart disease, chronic kidney disease, and obesity." (PMID 36423166, 2022). "ACE2 was similarly upregulated in the kidneys of mice with comorbid diabetes compared with aged controls, whereas TMPRSS2 (primarily distal nephron) was highest in telmisartan-treated animals." (PMID 34501332, 2021). "Asthmatics with this endotype suffer more often from comorbidities, such as obesity, diabetes mellitus and hypertension, and it has already been mentioned that some of these comorbidities are associated with a higher expression of ACE2 and TMPRSS2." (PMID 34945846, 2021). "Testosterone, TMPRSS2, and aromatase were independently associated (p < 0.01) with severity after adjusting for several baseline risk variables (including age, sex, CRP, obesity, hypertension, hyperlipidemia, and diabetes) in a multivariate logistic regression model." (PMID 39449074, 2024). "Asthmatics that were male, African American and had a history of diabetes mellitus presented higher expression of ACE2 and TMPRSS2." (PMID 34945846, 2021). "Experimental studies demonstrated that mice with diabetes have upregulated ACE2 and TMPRSS2 both in the lungs and the kidney." (PMID 34501332, 2021). "In contrast, mice with comorbid diabetes had heightened lung ACE2 and TMPRSS2 protein levels and increased lung ACE2 activity." (PMID 34501332, 2021). "We showed that mRNA of TMPRSS2 and ADAM10, ADAM17 and Furin as well as MAS were all up-regulated in the diabetic heart and may increase receptor internalization and shedding in diabetes." (PMID 33906662, 2021). "The TMPRSS2 inhibitor, Camostat, has been reported to correct some of the metabolic abnormalities present in rats with diabetes and obesity, however, it is not clear that these effects were specific to inhibition of TMPRSS2." (PMID 33042029, 2020). "Notably, diabetes facilitates SARS-CoV-2 viral entry into the heart via the overexpression of cellular angiotensin-converting enzyme 2 (ACE2) and Transmembrane serine protease 2 (TMPRSS2)." (PMID 36123740, 2022). "A positive correlation of ACE2 and DPP4 with TMPRSS2 was lacking in pancreatic cancer and diabetes." (PMID 33796097, 2021). "Notably, both ACE2 and TMPRSS2 are rarely expressed in single pancreatic β cells from donors with or without diabetes suggesting that SARS-CoV-2 cannot directly infect β cells." (PMID 33435929, 2021). "TMPRSS2 and aromatase were both increased in non-survivors and independently associated (p < 0.01) with mortality after adjusting for several baseline risk variables (including age, sex, CRP, hypertension, hyperlipidemia, and diabetes) in a multivariate logistic regression model." (PMID 39449074, 2024). "The correlation data for ADAM 10, TMPRSS2, ADAM17, and Furin, relative to diabetes or no diabetes levels is bifurcate." (PMID 33906662, 2021).
lung adenocarcinoma (29 papers, 2020 to 2025). A carcinoma that arises from the lung and is characterized by the presence of malignant glandular epithelial cells. "High level of NRP1 associates with worse prognosis in multiple cancers, while high level of TMPRSS2 is associated with better survival of Lung Adenocarcinoma (LUAD)." (PMID 34168096, 2021). "For example, other cancer types such as Lung Adenocarcinoma (LUAD) or Liver Hepatocellular Carcinoma (LIHC) may also exhibit increased susceptibility to COVID-19 infection via similar mechanisms governed by TMPRSS2, TMPRSS4, and TRIM31, however this remains to be further investigated." (PMID 35970857, 2022). "TMPRSS2 has been reported to be dysregulated in other tumours, such as prostate and lung adenocarcinomas." (PMID 37568724, 2023). "Calu-3 is widely used in SARS-CoV-2 in vitro assays as it is derived from a human lung adenocarcinoma and it has both receptors TMPRSS2 and ACE2, both important in the context of infection." (PMID 35734825, 2022). "In this perspective, the use of human lung adenocarcinoma cells expressing TMPRSS2 (Calu-3) is strongly recommended to avoid the onset of undesired mutations in the spike protein encoding gene including the CS." (PMID 36297209, 2022). "Quantitative real-time PCR (qRT-PCR) confirmed that TMPRSS2 was upregulated in lung adenocarcinoma (LUAD) and downregulated in breast invasive carcinoma (BRCA)." (PMID 35558557, 2022). "More specifically, TMPRSS2 was expressed lower in breast cancer samples and lung adenocarcinoma than that in normal samples with p value 0.000001 and 1.4E-07, respectively." (PMID 33061814, 2020). "In this study, we investigated the gene expression of angiotensin I-converting enzyme 2 (ACE2) and transmembrane serine protease 2 (TMPRSS2) with prognosis in lung adenocarcinoma (LUAD) and lung squamous cell carcinoma (LUSC)." (PMID 32345328, 2020). "A high expression of TMPRSS2 was significantly associated with a short overall survival in breast invasive carcinoma (BRCA), sarcoma (SARC), and uveal melanoma (UVM), as well as with a long overall survival in lung adenocarcinoma (LUAD)." (PMID 36364238, 2022). "In addition, androgen administration to a lung adenocarcinoma cell line up regulated the TMPRSS2 transcript more than two-fold, accompanied by an androgen dependent loading of the AR protein onto the TMPRSS2 enhancer." (PMID 33796068, 2021). "To test this we utilized A549 AAT cells, a lung adenocarcinoma cell line transduced to express ACE2 and TMPRSS2, since they support replication of all three VOCs." (PMID 37883246, 2023). "Since Calu-3 are human-derived lung adenocarcinoma cells, which is closer to the in vivo target of SARS-CoV-2 infection, they were used as a reference to compare the expression of ACE2 and TMPRSS2." (PMID 35746703, 2022). "Compared with the normal tissues, the expression of TMPRSS2 was higher in ESCA (esophageal carcinoma), KIRP (kidney renal papillary cell carcinoma), LUAD (lung adenocarcinoma), READ (rectum adenocarcinoma), and UCEC (uterine corpus endometrial carcinoma)." (PMID 35558557, 2022). "In human H1299 lung adenocarcinoma cells, we also evaluated the influence of the EOs on the gene expression of angiotensin-converting enzyme 2 (ACE2) and transmembrane protease serine 2 (TMPRSS2), which are involved in SARS-CoV-2 entry in human host." (PMID 33809983, 2021). "To explore the susceptibility factors of cancer patients, we assessed the expression of ACE2, TMPRSS2, and the endocytic regulator AAK1 in lung adenocarcinoma (LUAD) patients and explored their effects on immune infiltration." (PMID 33195212, 2020).
lung adenocarcinoma (continued). "A similar unmethylated pattern for TMPRSS2 promoter was evidenced in both lung adenocarcinoma (LUAD) and lung squamous cell carcinoma (LUAS) specimens, where expression levels of TMPRSS2 were significantly downregulated." (PMID 32967703, 2020). "As there can be drastic differences in small molecule retention and behavior in mammalian cell lines, two diverse cell lines, A549 lung adenocarcinoma cells made to overexpress ACE2 and TMPRSS2, and Huh7 hepatocellular carcinoma cells overexpressing ACE2, were employed for these assays." (PMID 39762652, 2025). "Notably, MS-275 was able to increase ACE2/TMPRSS2 expression and SARS-CoV-2 production, although to a lesser extent, also in the lung adenocarcinoma cell line Calu-3 cells." (PMID 38162580, 2023). "Similarly, androgen administration to a lung adenocarcinoma cell line upregulated TMPRSS2 transcripts and AR signaling inhibition reduced ACE2 and TMPRSS2 expression levels and SARS-CoV-2 viral entry." (PMID 37047226, 2023). "However, chloroquine did not inhibit SARS-CoV-2 infection in human lung adenocarcinoma cell line Calu-3 overexpressing TMPRSS2." (PMID 34055887, 2021). "A clinical TMPRSS2 inhibitor Camostat Mesylate, potently inhibited SARS-CoV and MERS-CoV, also excellently blocked SARS-CoV-2 entry in lung adenocarcinoma cell line Calu-3 at concentrations without obvious toxicity." (PMID 34055887, 2021). "Finally, the human lung adenocarcinoma alveolar basal epithelial cell line A549 expresses very low levels of both ACE2 and TMPRSS2, perhaps explaining why this cell line does not support infection by SARS-CoV-2 viral particles." (PMID 34200372, 2021).
Obesity (27 papers, 2017 to 2026). Accumulation of substantial excess body fat. "The general loss of tissue-dependent differences in both ACE2 and TMPRSS2 mRNA levels in animals fed a Western diet in the current study coincides with clinical observations linking obesity with COVID-19 infection and severity." (PMID 36656980, 2023). "In addition to furin, vascular endothelium also highly expresses the ACE2 receptor and the priming protease TMPRSS2, which make the endothelium of patients with obesity highly susceptible to SARS-CoV-2 infection." (PMID 32806722, 2020). "The association of obesity with death might be for a specific tumour subtype such as tumours with the TMPRSS2:ERG gene fusion." (PMID 28701188, 2017). "Several cardiovascular risk factors such as obesity, metabolic syndrome, visceral fat, and the Western diet increases androgen levels in male and female subjects; therefore, we speculate that they could enhance TMPRSS2 expression in human cells." (PMID 33182653, 2020). "In the context of obesity, TMPRSS2 also attenuates bioavailability of the ghrelin pathway and thereby suppresses GLP-1-mediated control of glucose homeostasis." (PMID 41842964, 2026). "Here we show that intestinal transmembrane serine protease 2 (TMPRSS2) plays a pivotal role in deregulating anti-diabetic GLP-1 production in obesity." (PMID 41842964, 2026). "ACE2, TMPRSS2, and NRP1 positively correlated with BMI in AS and/or E, while NRP1 correlated with age in T. In subcutaneous AT, ACE2 and NRP1 were more influenced by obesity while TMPRSS2 was more age-dependent." (PMID 40806445, 2025). "TMPRSS2 gene expression was found to be increased in lung epithelial cells and in pancreatic islets of subjects with obesity." (PMID 40806445, 2025). "TMPRSS2 expression in the airways of hypertension patients or in obesity remains to be investigated." (PMID 37208193, 2023). "Importantly, persistent TMPRSS2 and ADAM17 expression was shown, even after significant weight loss, reflecting the long-lasting impact of obesity on adipose tissue biology." (PMID 40806445, 2025). "Abnormal ACE2 expression, angiotensin II and angiotensin 1–7 imbalance, and TMPRSS2 androgen-mediated overactivity seem to be key regulators of SARS-CoV-2 infectivity, in accordance with epidemiological observations of hypertension, obesity, and male sex as being major risk factors." (PMID 32850920, 2020). "Furthermore, obesity may increase the expression of transmembrane protease, serine 2 (TMPRSS2), and angiotensin-converting enzyme 2 (ACE2) in the lower respiratory tract, facilitating the infection and respiratory complications." (PMID 38668323, 2024). "Furthermore, non-alcoholic fatty liver disease (NAFLD) is a major comorbidity of obesity, and it has been linked to increased hepatic expression of ACE2 and TMPRSS2, which could contribute to the aggravate morbidity in SARS-CoV-2 patients." (PMID 34684358, 2021). "Accordingly, a PAR2-mutant mouse resistant to TMPRSS2 cleavage is protected from GIP upregulation and diet-induced obesity." (PMID 41842964, 2026). "ACE2, TMPRSS2, ADAM17, and NRP1 are more expressed in visceral AT, with obesity significantly influencing their protein expression." (PMID 40806445, 2025). "In women with previous obesity, ACE2 and NRP1 levels decreased, while TMPRSS2 and ADAM17 remained unchanged." (PMID 40806445, 2025). "In the context of obesity and its related metabolic disturbances, elevated insulin levels, as observed in patient with insulin resistance and MetS, have been speculated to upregulate TMPRSS2 expression via phosphoinositide 3‐kinase/protein kinase B/androgen receptor signaling." (PMID 34269511, 2021). "In turn, TMPRSS2 expression appears to be more dependent on ageing rather than obesity, since its expression remains virtually the same in both older groups (with or without obesity), while it increases in comparison to the middle-aged control group." (PMID 40806445, 2025).
Obesity (continued). "TMPRSS2 levels increase with age (p = 0.0009, older group without obesity) to levels similar to those observed in obesity or after weight loss." (PMID 40806445, 2025). "Both TMPRSS2 and ADAM17 protein levels increase in older women with obesity, when compared to controls (p = 0.0013 and p = 0.0274, respectively), and do not differ significantly from middle-aged individuals with prior obesity." (PMID 40806445, 2025). "Moreover, the expression of TMPRSS2 and ADAM17 remains unchanged in individuals with previous obesity." (PMID 40806445, 2025). "However, studies on the direct relationship between obesity and nutrition with TMPRSS2 expression have never been made." (PMID 33182653, 2020). "Importantly, vascular endothelium in patients with obesity may highly express ACE2, TMPRSS2, and furin, which make it more vulnerable to SARS-CoV-2 infection, impairing this balance." (PMID 32806722, 2020). "Furthermore, the negative impact of obesity on PCa prognosis has mainly been observed in men with the TMPRSS2-ERG gene fusion implying an interaction." (PMID 29163372, 2017). "It is, however, unclear if, over a longer period, these patients would reach the levels of TMPRSS2 and ADAM17 observed in individuals without obesity." (PMID 40806445, 2025). "Moreover, despite there being evidence that obesity enhances the expression of ACE2 and TMPRSS2 in lung tissue, to the best of our knowledge, no studies have evaluated whether a KD can affect molecular steps involved in SARS-CoV-2 infection." (PMID 34684358, 2021).
breast carcinoma (17 papers, 2014 to 2024). "In the case of breast cancer, our analysis showed that TMPRSS2 had significantly low expression and low mutation frequency in tumour tissues, but its promoter methylation level was significantly increased." (PMID 34951103, 2022). "Our results show that the TMPRSS2 rs2276205 minor allele is associated with better survival in breast cancer patients; thus, the major allele impairs the prognosis." (PMID 25029565, 2014). "Silencing of TMPRSS2 causes sensitivity to tamoxifen, one of the most widely used drugs in treating breast cancer." (PMID 25029565, 2014). "In breast cancer studies, the migratory and metastatic behavior of tumor cells can be promoted by the regulation of TMPRSS2 and its downstream signal pathway in vitro." (PMID 36992839, 2023). "The results showed that high expression of TMPRSS2 in breast cancer has a poor prognosis in enriched CD4+ T cells (HR = 1.78 p < 0.01) and enriched CD8+ T cells (HR = 3.52 p < 0.001)." (PMID 35558557, 2022). "Briefly, in this part of the study, we found that there was a requirement for new methylated genes other than PAX5 and TMPRSS2 to measure the effects of methylation inhibitor in breast cancer tissue in in vitro models." (PMID 30792990, 2019). "The prognosis of the cancers analyzed by Kaplan-Meier plotter databases and GEPIA databases indicating that TMPRSS2 may serve as an independent risk factor to evaluate the prognosis of KIRP, LUAD, UCEC, LIHC, STAD, READ and breast cancer, or BRCA." (PMID 35558557, 2022). "Interestingly, the prognosis of LUAD and breast cancer affected by the TMPRSS2 expression is consistent with the respective prognosis based on immune cells." (PMID 35558557, 2022). "TMPRSS2, a member of the family of Type II transmembrane serine proteases, is expressed on lung, prostate, and breast cancer cells, and its expression is regulated by androgen receptors; the authors discussed potential TMPRSS2 targeting through pharmacological approaches." (PMID 33182653, 2020). "To address this hypothesis, we genotyped tagging SNPs (tagSNPs) of five TTSP genes, TMPRSS1, TMPRSS2, TMPRSS3, TMPRSS7, and TMPRSS11E, two other serine proteases uPA and PRSS8, and HGF, and investigated their association with breast cancer risk and patient survival." (PMID 25029565, 2014). "Meanwhile, a recent study pointed out that lower expression of TMPRSS2 is a prognostic marker for OS and DFS in breast cancer." (PMID 34951103, 2022). "In the patients with pulmonary metastases from breast cancer and papillary thyroid cancer, some of the cancer cells were positive for SARS-CoV-2 genomic and replicating RNA, ACE2, and TMPRSS2 RNA." (PMID 34440669, 2021). "The methylation rates in tissue DNA of patients with breast cancer were found between 33% and 58% for PAX5 gene and between 49% and 55% for TMPRSS2 gene according to ß-actin gene." (PMID 30792990, 2019). "In our study groups, we found that methylation rates of primary breast cancer tissues were 70% (7/10) for PAX5 and 60% (6/10) for TMPRSS2, respectively." (PMID 30792990, 2019). "In a previous study PAX5, TMPRSS2, and SBDS genes that we are investigating were reported to be methylated more than 60% in breast cancer and malignant melanoma cell lines." (PMID 30792990, 2019). "However, the high expression of TMPRSS2 showed a poor prognosis in READ (OS HR = 2.2, 95% CI = 1 to 4.84, p = 0.043), breast cancer (OS HR = 1.59, p = 0.0047), and BRCA (OS HR = 1.5, p = 0.015)." (PMID 35558557, 2022). "Interestingly, the prognosis of breast cancer and LUAD affected by the TMPRSS2 expression is consistent with the respective prognosis based on immune cells." (PMID 35558557, 2022). "However, the increased expression of TMPRSS2 showed a poor prognosis in READ, breast cancer, and BRCA." (PMID 35558557, 2022). "It was shown that PAX5 and TMPRSS2 were not suitable genes to measure the effects of methylation inhibitors in breast cancer tissue." (PMID 30792990, 2019).
breast carcinoma (continued). "In breast cancer, GSE9893, GSE7390, GSE12276 and GSE6532 datasets revealed that the patients with up‐regulated TMPRSS2 expression had significantly poor overall survival (OS), relapse‐free survival (RFS) and distant metastasis‐free survival (DMFS) compared to patients with lower TMPRSS2 expression." (PMID 34951103, 2022). "Whereas CL-14 already has been described to be permissive in a preprint, the breast carcinoma cell line CAL-51 with high levels of NRP1 beside ACE2 and TMPRSS2 expression and the colon carcinoma cell line CL-40 have not been identified before." (PMID 34339474, 2021). "However, the methylation status of selected PAX5, TMPRSS2, and SBDS genes was examined in cell lines but not primary tumor tissue of patients with breast cancer and malignant melanoma in the literature." (PMID 30792990, 2019).